MTHFD2 (methylenetetrahydrofolate dehydrogenase (NADP+ dependent) 2, methenyltetrahydrofolate cyclohydrolase)
Diseases named in the same sentence as MTHFD2 in open-access papers (continued):
Sharing a sentence is not in itself a finding about the gene and the disease.
cancer (continued). "Moreover, we found that MYCN mediated the folate cycle via MTHFD2, which contributed one-carbon unit to enhance purine synthesis, and further regulated nucleotide production by PAICS in response to cancer progression." (PMID 31624245, 2019). "DHFR and MTHFD2 were not downregulated in cancers, and they were upregulated in 6 and 9 cancers, respectively." (PMID 31828117, 2019). "MTHFD2 knockdown resulted in impaired cell migration and invasion into extracellular matrix as well as decreased the fraction of cells with a high CD44 expression, a marker of cancer stem cells." (PMID 23295955, 2013). "Since the biological consequences of MTHFD2 impairment in cancer cells had not been previously studied in detail, MTHFD2 was chosen for functional characterization." (PMID 23295955, 2013). "Some of these gene nodes have been shown to be functionally involved in other cancer types, including regulation of tumor cell proliferation (Creb, C/ebp, ATF3, ATF4), invasion (MTHFD2, FGF2) and metastasis (PTGS1/COX1, E-selectin, ATF3, FGF2, IL1A, MMP1, MMP13)." (PMID 24124450, 2013). "However, subsequent studies have reported that it is not as strongly selective for the MTHFD2 isozyme as desired and affects non-cancer cells." (PMID 41303507, 2025). "Could targeting the non-canonical function of MTHFD2 be therefore therapeutically useful in cancers?" (PMID 41303507, 2025). "Subsequent investigations found that although MTHFD2L is also found in cancer cells, it is expressed at much lower levels than MTHFD2, does not show the same pattern of pronounced upregulation in cancer cells, and is additionally not responsive to growth factors." (PMID 41303507, 2025). "In summary, MTHFD2 upregulation can be driven by various transcriptional, including mTORC1, MYC or Wnt/β-catenin signaling, post-transcriptional and post-translational mechanisms, although the mechanistic basis of this regulation appears to be cancer type specific." (PMID 40604332, 2024). "MTHFD2 is exclusively overexpressed in cancer cells but absent in most healthy adult human tissues." (PMID 39256448, 2024). "Therefore, inhibiting MTHFD2 may specifically affect and impair DSB repair in cancer cells versus normal." (PMID 38533616, 2024). "Because of the low expression of MTHFD2 in most adult tissues, targeting MTHFD2 is unlikely to produce significant side effects and MTHFD2 could be as a novel target for cancer therapy." (PMID 37936908, 2023). "Conversely, the absence of MTHFD2 in tumors may impair the malignant features of cancers and trigger cell death." (PMID 38130721, 2023). "Interestingly, the MTHFD2 inhibitors are highly effective in killing a subset of cancer cells, but not all, indicating that neither the MTHFD2 RNAi nor CRISPR‐Cas9 KO cells predict the effects using the inhibitors." (PMID 35583750, 2022). "MTHFD2 is highly expressed in cancer cells but not in healthy cells." (PMID 35613161, 2022). "Since the lymphatic system also has an immunomodulatory role to counteract cancer cells, combined with the fact that metabolism influences immune action, it is tempting to speculate that MCF-7 secretome upregulates MTHFD2 in LECs to evade and survive the immune insult." (PMID 35806196, 2022). "Thus, combination of MTHFD2 inhibitor and growth factor inhibitors might be a promising therapeutic strategy for EGFR inhibitor-resistant cancers." (PMID 32411609, 2020). "Notably, EBV upregulated MTHFD2, a mitochondrial enzyme not expressed by resting B cells or by most adult cells but among the most highly induced metabolic enzyme in human cancer." (PMID 31257153, 2019). "Nevertheless, several observations suggest that the known metabolic function of MTHFD2 may not be the sole explanation for its prominent role in cancer." (PMID 30275950, 2018).
cancer (continued). "Although chemical inhibitors of the MTHFD enzymatic activity have been reported, different strategies may be required if a non-enzymatic function of the MTHFD2 enzyme is critical for cancer cells." (PMID 30275950, 2018). "First, supplementing cultures with formate, the primary product of the mitochondrial pathway, fails to rescue MTHFD2 knockdown cancer cells, indicating that another function of the MTHFD2 protein might be necessary for growth." (PMID 30275950, 2018). "However, in recent years, it was reported that C1 metabolism in the mitochondria was markedly enhanced in a comprehensive gene analysis of cancer cell lines and tumor tissues of cancer patients, such as serine hydroxymethyltransferase 2 (SHMT2) and methylenetetrahydrofolate dehydrogenase 2 (MTHFD2)." (PMID 30582043, 2018). "One potential explanation for the effective killing with MTHFD2 RNAi but not with CRISPR‐Cas9 could be that cancer cells acutely rely on MTHFD2 to generate thymidine, but easily switch to use the SHMT1 pathway, allowing the clones to survive long term as in the case of CRISPR‐Cas9 KO cells." (PMID 35583750, 2022). "Although no inhibitor for MTHFD2 has yet emerged, its overexpression in rapidly replicating tumor tissues but not in normal tissues and the finding that knockdown of MTHFD2 effects a strong antiproliferative response in tumor cells provide compelling rationale for targeting MTHFD2 in cancer." (PMID 30867007, 2019). "However, there seems to be clear differences in MTHFD2 expression between samples from the same as well as different cancer types since MTHFD2 expression could not be detected in all tumor samples analyzed, indicating heterogeneity in MTHFD2 expression." (PMID 23295955, 2013). "This may indicate that the effect of MTHFD2 on epigenetic modifications may be different in cancer cells and immune cells, or that the increased methylation observed in this particular T cell subtype is an indirect rather than a direct consequence of MTHFD2 inhibition." (PMID 40604332, 2024). "Furthermore, MTHFD2 was observed to be positively correlated with infiltrations of several immune cells in various cancers, especially the activated CD4+ T cell and type 2 T helper cell, which were significant in almost all cancers, suggesting that MTHFD2 might be related to the inflamed TME." (PMID 38130721, 2023). "Interestingly, this mitochondrial enzyme is overexpressed in rapidly growing tumor tissues and not in replicating normal tissues, and the knockdown of MTHFD2 has an antiproliferative effect, suggesting that the inhibitors of this enzyme may be employed in cancer treatment." (PMID 26907355, 2016). "As MTHFD2 inhibitors do not introduce RS in nontumorigenic cells, we propose that their combination with ATR or Chk1 inhibitors may improve the cancer selectivity and therapeutic index of these compounds." (PMID 35228749, 2022).
tumor (97 papers, 2013 to 2026). "Higher SLC1A5 or MTHFD2 expression levels were associated with higher KIRC tumor stage and higher KIRC lymph node metastasis likelihood." (PMID 39958609, 2024). "Higher KIRC SLC1A5 or MTHFD2 expression levels were associated with higher tumor stages, increased lymph node metastasis possibilities, poorer OS, and poorer RFS." (PMID 39958609, 2024). "This multifaceted approach not only underscores the potential involvement of MTHFD2 loss in propelling a senescent state but also highlights its potential significance in modulating tumor behavior." (PMID 39668825, 2024). "Since SHMT2 and MTHFD2 were consistently upregulated in undifferentiated thyroid cancer and strongly positively correlated with tumor size, we evaluated the associations of these genes with clinico-pathological features." (PMID 38331894, 2024). "Considering the tumor subtypes separately, the ccRCC maintained a significant association between MTHFD2 expression and Fuhrman grade (Odds ratio = 4.364; 95%CI: 1.719–11.079; p = 0.001)." (PMID 38422037, 2024). "Folate and glutamine metabolism-related genes, especially SLC1A5 and MTHFD2, were associated with the prognosis, tumor stage, and lymph node metastasis status in KIRC." (PMID 39958609, 2024). "Further correction analysis demonstrated that MTHFD2 level was associated with tumor immune infiltration." (PMID 37484807, 2023). "The results confirmed the MTHFD2 expression levels to be positively associated with tumor-infiltrating immune cells." (PMID 36726381, 2023). "The results showed that MTHFD2 was significantly associated with tumour cell cycle, invasion, migration and immune system regulation in BC." (PMID 37480214, 2023). "High levels of MTHFD2 have been associated with tumor recurrence and worse prognosis in multiple solid and liquid malignancies and participate in resistance against gemcitabine and pemetrexed." (PMID 35888776, 2022). "MTHFD2 is generally regarded as the enzyme responsible for mitochondrial NADPH production to overcome oxidative stress and maintain redox homeostasis in tumor cells, and MTHFD2 deficiency can induce mitochondrial dysfunction." (PMID 35382861, 2022). "Subsequently, we used TISIDB database to further explore the association between MTHFD2 expression level and 28 tumor immune infiltrating cell subtypes." (PMID 35135596, 2022). "The expression level of MTHFD2 was positively associated with age and tumor grade." (PMID 35135596, 2022). "MTHFD2 also might be a new target of anti-tumor immunity for its strong association with immune infiltration." (PMID 35581573, 2022). "Moreover, expression of MTHFD2 was positively associated with tumour stage and negatively associated with survival time in LUAD patients." (PMID 34121323, 2021). "We then examined whether MTHFD2‐depleted cells could be less tumorigenic in nude mouse xenografts and observed the suppression of in vivo tumor development by MTHFD2 deficiency." (PMID 34231329, 2021). "Similarly in RCC and HCC, MTHFD2 was upregulated in tumor tissues and associated with pathological characteristics including TNM staging, diseased recurrence and patient survival." (PMID 32411609, 2020). "Alternatively, introducing MTHFD2 could markedly rescue cell growth caused by SOX7 overexpression, suggesting that MTHFD2 inhibition played a key role in SOX7-mediated tumor suppression." (PMID 29757932, 2018). "MTHFD2 is a robust biomarker for poor prognosis in ccRCC, influencing tumor-immune interactions and macrophage polarization." (PMID 41752156, 2026). "Targeting STAT6 or MTHFD2 suppressed tumor growth in TKIs-resistant patient-derived xenograft models." (PMID 41484064, 2026). "In tumor cells, MTHFD2 can efficiently drive the folate cycle and stimulate PDL1 expression to promote tumor immune escape." (PMID 40740648, 2025).
tumor (continued). "Collectively, our results indicate the existence of a positive feedback loop between UHMK1 and MTHFD2, sustaining continuous activation of this signaling pathway and facilitating tumor progression." (PMID 40918462, 2025). "The unique expression pattern of MTHFD2—markedly upregulated in several tumour types but considerably limited in most healthy adult tissues—positions it as a key candidate for precision medicine strategies." (PMID 41303507, 2025). "Model 2 for the entire study cohort included the covariates ECOG performance status, tumor differentiation, MTHFD2 expression, and chemotherapy regimen, listed in descending order of impact on the PFS hazard ratio." (PMID 40357991, 2025). "The expression levels of genes ESRP1, GRHL2, MTHFD2, RACGAP1, and SQLE, considered risk factors, were significantly up‐regulated in tumor tissues compared with normal tissues and were statistically significantly associated with a poor prognosis." (PMID 40586163, 2025). "Altogether, our study highlights the critical role of MTHFD2 in redox homeostasis and tumor progression, demonstrating the therapeutic potential of targeting MTHFD2." (PMID 38723197, 2024). "Further investigation into the mechanisms of deiodination and the development of strategies to counteract this process will be essential for the advancement of [125I]anastrozole and [125I]epirubicin as targeted radiopharmaceuticals for MTHFD2-driven neoplasms." (PMID 38794278, 2024). "We investigated this possibility by employing B16F10 cells with MTHFD2 knockdown in a subcutaneous tumor model." (PMID 39668825, 2024). "Despite the accessible and simple results provided by immunolabeling, few reports have explored in situ MTHFD2 expression to evaluate tumor prognosis." (PMID 38422037, 2024). "Studies on TCGA databases highlighted the MTHFD2 overexpression in tumor samples compared to NN ones." (PMID 38422037, 2024). "Although MTHFD2 immunolabeling suggests tumor aggressiveness, it needs to be validated in other cohorts as potential prognostic factor." (PMID 38422037, 2024). "Within the 8 Mitochondrial-Related Genes (MRGs) analyzed, ACSL1, MTHFD2, and MRPL13 were notably overexpressed in both the high-risk group and tumor tissues." (PMID 38310106, 2024). "Our results suggest that folate metabolism- and glutamine metabolism-related genes, especially SLC1A5 and MTHFD2, are associated with KIRC prognosis, tumor stage, and lymph node metastasis status." (PMID 39958609, 2024). "our study highlights the crucial role of MTHFD2 in redox regulation and tumor progression, demonstrating the therapeutic potential of targeting MTHFD2." (PMID 38723197, 2024). "Perturbation of folate metabolism by depletion of MTHFD2 promotes the differentiation of regulatory T-cells (Tregs), which can have tumour supportive function." (PMID 38698089, 2024). "As a result, the overexpression of MTHFD2 or TYMS significantly enhanced the tumor cell proliferation rate, whereas the tumor cell growth promoted by MTHFD2 or TYMS overexpression was decreased by the overexpression of MTR." (PMID 39039072, 2024). "This study investigated the MTHFD2 expression in different RCC cohorts, associating it with tumor characteristics and prognostic factors." (PMID 38422037, 2024). "Herein, we investigated the MTHFD2 mRNA and protein expression profiles in RCC cohorts, associating them with tumor characteristics and prognostic factors." (PMID 38422037, 2024). "Ferrostatin-1 (Fer-1), a ferroptosis inhibitor, was added to investigate the role of ferroptosis in MTHFD2-related regulation of tumor cell proliferation in TNBC cell lines." (PMID 36726381, 2023). "Given the association between MTHFD2 and the tumor immune microenvironment, we further investigated the potential of MTHFD2 in predicting tumor immunotherapies, such as ICB therapy." (PMID 38130721, 2023). "The potential mechanisms by which MTHFD2 knockdown suppressed tumor cell proliferation and increased apoptosis were also investigated." (PMID 36726381, 2023).
tumor (continued). "On unpaired and paired analysis, we found the expression levels of MTHFD2 to be increased in the majority of tumor tissues in contrast to normal tissues." (PMID 36726381, 2023). "MTHFD2 is a mitochondrial one-carbon metabolism enzyme highly expressed in several human tumors, and targeting MTHFD2 has been used as the target of tumor therapy." (PMID 37936908, 2023). "In glioma, miR-940 suppresses tumor progression by inhibiting mitochondrial folate metabolism, which directly targets MTHFD2." (PMID 37147729, 2023). "To demonstrate the function of MTHFD2 in vivo, we established a T24 xenograft tumour model in nude mice." (PMID 37480214, 2023). "In the present study, we analyzed the MTHFD2 expression level in EC and found that both MTHFD2 mRNA and protein expression levels were up-regulated in tumor tissues compared with normal adjacent tissues." (PMID 37484807, 2023). "It has been shown that increased expression of MTHFD2 and PSAT1 is associated with enhanced metabolism and survival, and it is often evident in tumor ECs." (PMID 36766885, 2023). "mRNA levels, evaluated through RT-qPCR, showed the mitochondrial enzymes SHMT2 and MTHFD2 differentially expressed in tumor samples of cSCC, the most aggressive NMSC." (PMID 36964165, 2023). "We found that the increased expression of MTHFD2 was significantly correlated with T stage (p < 0.001), M stage (p = 0.028), histologic grade (p < 0.001), tumour subtype (p < 0.001) and pathologic stage (p < 0.001)." (PMID 37480214, 2023). "Accumulating evidence indicates that MTHFD2 is related to tumourigenesis, tumour development, poor disease outcomes and drug resistance." (PMID 37480214, 2023). "The expression of effector genes of these anti-tumor TIICs was also positively related with MTHFD2 expression." (PMID 38130721, 2023). "The potential tumour‐suppressor role of MTHFD2 has recently been reported in GBM cells via the inhibition of ERK1/2 phosphorylation." (PMID 37635346, 2023). "Remarkably, with respect to other histologic subtypes, we find that folate-mediated one-carbon metabolism and its key gene, MTHFD2, are upregulated in tumor cells from the solid subtype." (PMID 36138435, 2022). "Previous study reported that Carolacton (a natural product of MTHFD2 inhibitor tool compound) was able to restain the growth of different human tumor cell lines." (PMID 35581573, 2022). "More importantly, immunohistochemical staining further verified at the clinical sample scale that the density of MTHFD2 was increased in tumor regions of the solid pattern compared to the lepidic/acinar pattern." (PMID 36138435, 2022). "In conclusion, we describe first-in-class potent MTHFD2 inhibitors targeting thymidine synthesis preferentially in tumor cells through a new mechanism of action targeting the DDR." (PMID 35228749, 2022). "Otherwise, the anti-tumor mechanisms of MTHFD2 and the potential targets for immunotherapy in UCB need to be elucidated via molecular experiments." (PMID 35581573, 2022). "HIF-2α in turn can bind to the promoter region of MTHFD2 gene, and its overexpression increases the level of MTHFD2, thus forming a positive feed-forward loop to promote metabolic recombination and tumor progression." (PMID 35022030, 2022). "We found that the mRNA expression levels of ABCA1 and MTHFD2 genes in TAMs increased significantly with tumor progression." (PMID 36248907, 2022). "Upregulated MTHFD2 was reported to support multiple tumor phenotypes, including proliferation, migration, invasion, metastasis, drug resistance, immune evasion, metabolic reprogramming, self-renewal, and poor prognosis of patients." (PMID 36051358, 2022). "MTHFD2 is a folate-coupled metabolic enzyme, which has been proved to participant in the metabolic reprogramming and tumor cell-sustaining proliferative capacity." (PMID 35135596, 2022). "Both MTHFD2 and SHMT2 overexpression have been associated with tumor pathogenesis and poor survival." (PMID 34341479, 2022).